NLGN3 (neuroligin 3)
Diseases named in the same sentence as NLGN3 in open-access papers (continued):
Sharing a sentence is not in itself a finding about the gene and the disease.
glioma (continued). "In these mice, neuroligin-3 (Nlgn3) is shed in the Nf1-mutant (Nf1+/neo) optic nerve in an activity-dependent manner, such that genetic or pharmacological blockade of Nlgn3 shedding inhibits glioma initiation and progression." (PMID 35589737, 2022). "Moreover, NLGN3 significantly induced glioma cell migration, evidenced by an increased number of migrated cells in “Transwell” tests, which was reversed by Gαi1/3 DshRNA." (PMID 34373757, 2021). "Gαi1/3 mediation of NLGN3-induced signaling is essential for glioma growth in vitro and in vivo." (PMID 34373757, 2021). "Similarly, NLGN3 has been shown to be secreted in an activity-dependent manner in glioma, promoting cell division and glioma growth." (PMID 34911933, 2021). "Importantly, Gab1 silencing inhibited NLGN3-induced downstream signaling activation in glioma cells." (PMID 34373757, 2021). "Furthermore, the increase in glutamate release stimulates peritumoral neurons to release BDNF and Neuroligin 3 (NLGN3) that in turn stimulate the glioma cells to proliferation and infiltration and sustained NGS formation." (PMID 34489641, 2021). "For example, the microenvironmental synapse protein NLGN3 stimulates glioma growth by activating multiple oncogenic pathways (e.g., focal adhesion kinase activated upstream of PI3K-mTOR) and inducing transcriptional changes (e.g., upregulation of synapse-related genes in glioma cells)." (PMID 34804909, 2021). "Therefore, Gαi3, similar to Gαi1 26, is upregulated in human glioma tissues, correlating with poor survival, high tumor grade and NLGN3 upregulation." (PMID 34373757, 2021). "To elucidate whether NLGN3 affects the metastatic potential of glioma cells, we further investigated the effects of NLGN3 on migration using wound healing and on invasion by transwell assay." (PMID 34485271, 2021). "Importantly, patient-derived pediatric glioblastoma xenografts to the frontal cortex demonstrate a notable inhibition of glioma growth in Nlgn3 KO mice for up to 6 months." (PMID 34690695, 2021). "First, we investigated the expression of NLGN3 in glioma by IHC detection of tissue microarray." (PMID 34485271, 2021). "Similarly in established (U251MG) or primary human glioma cells, NLGN3-induced Akt-mTORC1 and Erk-MAPK activation was inhibited by Gαi1/3 shRNA, but enhanced with ectopic Gαi1/3 overexpression." (PMID 34373757, 2021). "The NLGN3/LYN/ADAM10 axis promotes glioma progression via a positive feedback loop." (PMID 34485271, 2021). "Additionally, NLGN3-activated glioma cells produce feedforward expression of NLGN3 to further increase glioma cell growth and proliferation 17-19." (PMID 34373757, 2021). "Nlgn3 protein can function as a cortical neuronal activity-regulated glioma mitogen." (PMID 34690695, 2021). "Using immunohistochemical analysis, we determined that NLGN3 was expressed abnormally highly in glioma tissues, suggesting that glioma-derived NLGN3 might be involved in glioma progression." (PMID 34485271, 2021). "Xenografts derived from high-grade primary human glioma cells failed to grow in a NLGN3-deficient brain 18, demonstrating that NLGN3 is required for glioma cell growth." (PMID 34373757, 2021). "The expression of NLGN3 in glioma was detected using immunohistochemistry." (PMID 34485271, 2021). "For example, studies have reported that synaptic molecule neuroligin‐3 (NLGN3) could promote glioma proliferation by the PI3K‐mTOR pathway." (PMID 33047898, 2020). "This may bear some interesting implications in the evolving theory that suggests neuronal activity leads to NLGN3-dependent sustained NGS formation in glioma." (PMID 33187183, 2020). "Accordingly neuronal activity has been reported to be potentially involved in glioma progression, via the activity of neuroligin-3 (NLGN-3), which appears to promote tumour progression through, at least partly, the PI3K-mTOR pathway, with links to focal adhesion kinase activation." (PMID 32366909, 2020).
glioma (continued). "Indeed, gliomas fail to grow in NLGN3 knockout mice, while blocking NLGN3 release prevents tumor growth in animals." (PMID 31953611, 2020). "Through the mTOR pathway, targeting NLGN3 secretion promoted the proliferation of gliomas." (PMID 33015162, 2020). "The protein neuroligin-3 (NLGN3) has been suggested to play a key role in glioma growth." (PMID 31953611, 2020). "NLGN3 has been suggested to play a key role in glioma growth and might therefore be a viable treatment target." (PMID 31953611, 2020). "Thus, NLGN3 mediates an autocrine/paracrine loop in glioma cells that perpetuates tumoral features (reviewed in the work by Johung and Monje)." (PMID 31846454, 2019). "We measured the expression of NLGN3 in serum EVs from glioma patients (n =18) and healthy individuals (n =9) and found that the mRNA level of NLGN3 was significantly higher in glioma patients than in healthy donors (**P < 0.01), although the mRNA level of NLGN3 varied between each glioma patient." (PMID 31410219, 2019). "However, further investigation is still needed to explore the reason for the large variation in the expression of NLGN3 in individual glioma patients." (PMID 31410219, 2019). "By activating PI3K‐mTOR pathway, NLGN3 can promote the proliferation of gliomas." (PMID 29777576, 2018). "NLGN3 expression in glioma tissue was semi-quantitatively assessed by immunohistochemistry." (PMID 30094719, 2018). "Another point of discussion is that NLGN3 may well be expressed in a heterogeneous manner in the glioma tissue." (PMID 30094719, 2018). "Notably, NLGN3 induces a feedforward loop that further enhances its own expression in glioma cells." (PMID 40076738, 2025). "Notably, this NLGN3-induced proliferation was attenuated by first pre-treating glioma cells with ADAM10 inhibitor, even in the presence of NLGN3, consistent with the hypothesized role for ADAM10-mediated CSPG4 cleavage in the NLGN3-CSPG4-PIEZO1 mechanism." (PMID 40791371, 2025). "However, a number of pressing questions remain that include mechanisms by which NLGN3 interacts with and signals to the glioma cell, whether similar interactions occur on healthy OPCs, and what role NLGN3 shedding may play in healthy oligodendroglial biology." (PMID 40791371, 2025). "Notably, NLGN3 is not the exclusive regulator of activity-dependent glioma growth, as NLGN3 deficiency only partially attenuates glioma cell mitogenic potential rather than completely abolishing it." (PMID 41018101, 2025). "Hence, NLGN3 is likely a key neuron-derived factor that regulates glioma growth." (PMID 38254206, 2024). "However, current research is limited to neuron-derived NLGN3 in the brain tumor microenvironment; whether NLGN3 secreted by tumor tissue itself can affect the growth of glioma cells remains unknown." (PMID 34485271, 2021). "Therefore, Gαi1/3 and NLGN3 upregulation in glioma tissues might be derived from both glioma cells and possible other cells in the tumor bulk (immune cells, endothelial cells and cancer stem cells, etc)." (PMID 34373757, 2021). "With evidence that NLGN3 induces expression of various synaptic genes in glioma cells, workers continued to probe the possibility that glioma cells and neurons synaptically engage one another and that this putative interaction could also serve as a hallmark of activity-dependent glioma progression." (PMID 33187183, 2020). "Additionally, previous research suggested that the secretion of NLGN3 could promote glioma growth, and we found that its binding partners are also highly expressed in tumor cells." (PMID 31118022, 2019). "Moreover, NLGN3 expression was assessed through immunohistochemistry of resected glioma tissue." (PMID 30094719, 2018). "In addition, our results suggest that (global) brain activity may be a viable treatment target in glioma, possibly in addition to inhibition of NLGN3 secretion." (PMID 30094719, 2018).
glioma (continued). "Indeed activity-induced secretion of Neuroligin 3 (from an unknown source) induced further Neuroligin 3 expression in the glioma cells, further driving proliferation." (PMID 26498877, 2016). "A recent study suggests that optogenetic stimulation of neurons enhances the expression of neuroligin-3 (NLGN3), which, in turn, promotes tumor cell proliferation through the PI3K-mTOR tumor-intrinsic pathway in patient-derived xenograft glioma models." (PMID 41268299, 2025). "Follow-up work found that patient-derived gliomas (including DIPG) fail to grow or exhibit delayed growth in NLGN3-knockout mice, highlighting their dependency on neuron-derived NLGN3." (PMID 41460355, 2025). "Across multiple clinically and molecularly distinct forms of paediatric and adult gliomas, activity-regulated paracrine factors such as BDNF and shed neuroligin 3 promote glioma growth." (PMID 39972132, 2025). "Neuronal factors like neuroligin‐3 (NLGN3), brain‐derived neurotrophic factor (BDNF), and insulin‐like growth factor‐1 (IGF‐1) stimulate glioma proliferation." (PMID 40685688, 2025). "PIWIL4 has been shown to promote neuronal differentiation in stem cell models and modulate glioma-related factors such as PTN and NLGN3." (PMID 41228218, 2025). "Taken together, these findings support the idea that that targeting the NLGN3 pathway, including PIEZO1 and ADAM10-mediated cleavage events, represent therapeutic strategies for gliomas." (PMID 40791371, 2025). "Synaptogenic factors, such as neuroligin-3 and BDNF, further enhance glioma proliferation and synapse formation." (PMID 41595608, 2025). "This intricate interplay between neurons and glioma cells, mediated by paracrine signals such as BDNF, NLGN3, and IGF‐1, underscores the complexity of the TME in brain tumors and highlights potential therapeutic targets for future interventions." (PMID 39469896, 2024). "Neuronal release of activity-dependent soluble factors, such as glutamate, neuroligin-3 (NLGN3), and brain-derived neurotrophic factor (BDNF), promote glioma progression." (PMID 38193532, 2024). "Neuronal activity-induced cleavage of NLGN3 from neurons and oligodendrocyte precursor cells (OPC) promoted glioma proliferation through PI3K-mTOR pathway, and NLGN3 derived from neurons and OPC stimulate feed forward expression of NLGN3 in cancer cell." (PMID 37443071, 2023). "The study of paracrine interactions between the nervous system and glioma cells has centered on the roles of brain-derived neurotrophic factor (BDNF) and neuroligin 3 (NLGN3)." (PMID 36968288, 2023). "Optogenetic promotion of optic pathway glioma growth was mediated in these low-grade gliomas by BDNF and NLGN3 secretion, which in turn was promoted by retinal activity." (PMID 36968288, 2023). "Soluble NLGN3, released from post-synaptic neurons, promotes feedforward increases in the expression of NLGN3 through activation of the PI3K-mTOR pathway in glioma cells." (PMID 37705736, 2023). "Neuroligin-3 (NLGN3) is a protein, secreted in an activity-dependent fashion, that has been identified as a mitogen in optogenetic studies of neuron-glioma synapses." (PMID 36614191, 2023). "NLGN3 can activate multiple RTKs and the downstream cascades (i.e. PI3K-Akt-mTOR), promoting cell survival and growth in glioma cells." (PMID 37880221, 2023). "The neuroligin-3 (NLGN3)-stimulated PI3K/mTOR pathway, which is activated by active neurons, aids in the formation of high-grade gliomas." (PMID 37569598, 2023). "For example, the discovery of neuron-glioma synapses and interplay between neuron and glioma cells highlights the vital roles of neurotransmitters and synaptic proteins in promoting GBM progression, such as NLGN3." (PMID 38596241, 2023). "In particular, glioma cells likely take advantage of the secretion of trophic factors, such as brain-derived neurotrophic factor (BDNF) and neuroligin-3 (NLGN3), which are regulated by neuronal activity." (PMID 35740334, 2022).
glioma (continued). "Neuronal activity stimulates NLGN3 extracellular domain shedding into the tumor microenvironment by the protease ADAM10 (A Disintegrin and Metalloprotease 10), thus inducing glioma growth." (PMID 36056393, 2022). "Neuroligin-3 (NLGN3), a postsynaptic cell-adhesion protein, was recently identified as a key factor in the interaction between the brain’s neurons and glioma cells." (PMID 35148403, 2022). "Here, the neurons surrounding the tumor secrete neuroligin-3, which promotes the formation of neuron–glioma synapses with a specific type of glutamate receptors, AMPA-receptors, on the glioma cells." (PMID 33466373, 2021). "Studies have shown that NLGN3 induces phosphorylations of multiple RTKs as well as downstream PI3K-Akt-mTOR and Erk-MAPK cascades, responsible for glioma cell growth and proliferation." (PMID 34373757, 2021). "Neurons and OPCs produce NLGN3 by cleavage of ADAM10 sheddase, so the inhibition of this enzyme blocks NLGN3 secretion into the tumor microenvironment and suppresses glioma outgrowth in preclinical models." (PMID 34532286, 2021). "Approximately 10% of glioma cells had developed neuro-glioma synapses (NGS), and that the development of these synapses was reduced in NLGN3 KO mice." (PMID 33187183, 2020). "NLGN3 was also found to stimulate FAK upstream of PI3K/mTOR and increased synapse-related genes in the glioma cells." (PMID 33187183, 2020). "One of these signals is Neuroligin-3 (NLGN3), a synaptic protein that is cleaved and secreted after neuronal activity and promotes PI3K- Target of Rapamycin (TOR) signaling, stimulating glioma growth." (PMID 31846454, 2019). "Neuroligin-3 is a tumor growth promoting protein and is secreted through neuronal activity and induces NLGN3 expression in glioma cells." (PMID 30094719, 2018). "ADAM10 is the protease enzyme that cleaves NLGN3 and treatment with small-molecule inhibitors of ADAM10 markedly decreased glioma growth in experimental model systems." (PMID 30279357, 2018). "While NLGN3 and neuronal activity-related factors are promising therapeutic targets, their current mechanistic understanding mostly comes from glioma/neuro-oncology and not from melanoma-specific experimental studies." (PMID 41463339, 2025). "Additionally, s-NLGN3 activates the PI3K-mTOR pathway, thereby promoting the proliferation and migration of glioma cells." (PMID 41018101, 2025). "We next investigated whether the observed interaction between NLGN3 and CSPG4 is necessary for the NLGN3-induced changes in glioma, such as glioma proliferation and growth." (PMID 40791371, 2025). "Targeting NLGN3 and IGSF-3 could present potential therapeutic strategies to inhibit glioma progression and epileptiform activity." (PMID 39201639, 2024). "NLGN3 was shown to activate Akt-mTOR, Erk-MAPK, and other signaling cascades in glioma cells." (PMID 37880221, 2023). "NLGN3 is cleaved by ADAM10 (A Disintegrin and Metalloproteinase 10) and is secreted from neurons, inducing phosphorylation and activation of several key receptor tyrosine kinases (RTKs) and downstream signaling cascades in glioma cells." (PMID 37880221, 2023). "Thus, there are multiple ways in which excitatory signaling contribute to malignant behavior in glioma, including AMPA and NMDA activation, limited GABAergic signaling, and neuroligin-3 secretion." (PMID 36614191, 2023). "Co-culture with neurons elicits a robust increase in glioma cell proliferation rate from around 20% to around 60%, underscoring the powerful effects of neurons on glioma proliferation that include neuroligin-3 (NLGN3) signalling and neuron-to-glioma synaptic mechanisms." (PMID 37914930, 2023). "The secreted ectodomain of Nlgn3 can act on glioma cells via unknown binding partners and recruits the phosphoinositide 3-kinase (PI3K)-mTOR pathway to promote glioma cell proliferation." (PMID 34690695, 2021).
glioma (continued). "In addition, we found that the expression of ADAM10 in glioma and normal brain tissue was positively correlated with the levels of LYN and NLGN3." (PMID 34485271, 2021). "Interestingly, Nlgn3 extracellular ectodomain functions as a cortical neuronal activity-regulated glioma mitogen promoting high-grade glioma (HGG) proliferation and growth (see Section “Nlgn3 in tumors”)." (PMID 34690695, 2021). "Conversely ectopic overexpression of Gαi1 and Gαi3 in P1 glioma cells significantly increased NLGN3-induced phosphorylation of Akt and S6K, without affecting their expression." (PMID 34373757, 2021). "NLGN3 promoted N-cad expression and inhibited E-cad expression, indicating its involvement in the EMT process and its role in the development and metastasis of glioma." (PMID 34485271, 2021). "We determined that NLGN3 is highly expressed by glioma tissue itself, but NLGN3’s role and the mechanism involved in glioma progression have not been reported." (PMID 34485271, 2021). "Neuroligin-3 (NLGN3) is necessary and sufficient to promote glioma cell growth." (PMID 34373757, 2021). "However, the authors applied the inhibitor to block the cleavage and secretion of the synaptic adhesion molecule neuroligin-3 (NLGN3), and thereby, reduced its growth promoting function rather specific for glioma cells." (PMID 34070094, 2021). "In order to investigate the role of NLGN3 in glioma, NLGN3-specific siRNA was transferred into the U87 and U251 cells to generate NLGN3 knockdown cells with negative-siRNA as control." (PMID 34485271, 2021). "In a subsequent study, the authors uncovered that glioma cells derived from pediatric glioma, diffuse intrinsic pontine glioma, and adult glioblastoma did not grow in NLGN3 knockout mice." (PMID 33187183, 2020). "The absence of NLGN3 significantly impedes the progression of both high- and low-grade gliomas." (PMID 40092993, 2025). "Recent studies have highlighted the importance of the glioma–neuron interactions in this process, showing that the glioma cells are synaptically integrated to the normal neuronal circuitry and receive survival signals through neuronal secretion of BDNF and NLGN3." (PMID 40867165, 2025). "Therefore, we sought to determine whether shed ectodomains of NLGN3 and CSPG4 are detectable in cerebrospinal fluid (CSF) of human glioma patients." (PMID 40791371, 2025). "Additionally, inhibition of ADAM10 prevents the release of NLGN3 into the TME, thereby suppressing high-grade glioma xenograft growth by blocking NLGN3-mediated activation of the phosphoinositol 3-kinase (PI3K)/mechanistic target of rapamycin (mTOR) signaling pathway." (PMID 41163091, 2025). "We then immobilized the NLGN3 ectodomains on commercial streptavidin resin Next, we isolated and solubilized membranes from patient-derived cell cultures of DIPG/DMG or adult GBM and passed each glioma membrane sample through the column in separate experiments." (PMID 40791371, 2025). "We postulated that NLGN3 expressed by older organoids was responsible for this behavior and, indeed, the addition of NLGN3 to young organoids fostered CSC tropism for the organoid, while the administration of an ADAM10 inhibitor prevented the integration of glioma cells into mature organoids." (PMID 37511496, 2023). "In malignant high-grade gliomas, neuronal activity leverages the ADAM10/neuroligin-3 axis to drive tumor growth, which has led to a clinical trial that evaluates an ADAM10 inhibitor (INCB7839) in treating recurrent or progressive pediatric high-grade gliomas (NCT04295759)." (PMID 37891793, 2023). "In addition, glioma cells interact with peritumoral excitatory neurons forming functional bona fide AMPA-mediated synapses, through which pro-mitotic peptides as NLGN3 can stimulate glioma progression." (PMID 34690699, 2021). "While the role of autocrine NLGN3 in glioma has not been well-studied." (PMID 34485271, 2021).